AXL (AXL receptor tyrosine kinase)
Diseases named in the same sentence as AXL in open-access papers (continued):
Sharing a sentence is not in itself a finding about the gene and the disease.
cancer (continued). "AXL signaling is involved in many cellular processes, including survival, migration, invasion, and metastasis in both normal and cancer cells." (PMID 26573603, 2015). "Inhibiting AXL pathway by using specific silencing RNA or a pharmacologic approach with foretinib, we demonstrated that cancer cell proliferation and migration was significantly suppressed." (PMID 25966280, 2015). "AXL is overexpressed in several human cancers, including various leukemias and solid tumours, where it is associated with a poor prognosis." (PMID 25966280, 2015). "AXL has been reported to be overexpressed in a variety of cancers and to promote cancer cell proliferation, migration, invasion, and survival and has drawn much attention as a potential therapeutic target in cancer." (PMID 26356563, 2015). "Following its identification as a transforming gene in human chronic myelogenous leukemia, AXL has been shown to be overexpressed in several types of human cancers such as lung and gastric cancers." (PMID 25593196, 2015). "Among AXL positive cases, 111 (65%) showed high expression levels (staining in ≥20% cancer cells), whereas 35% showed low expression (staining in < 20% cancer cells)." (PMID 25966280, 2015). "These events consequently inhibit the growth of cancer cells by down-regulating the AXL downstream signaling pathway." (PMID 25760142, 2015). "Mechanistic studies show that CUDC-101 integrates HDAC and EGFR/HER2 pathway inhibition, blocks and inhibits MET- and AXL-mediated signaling, and reduces cancer cell migration." (PMID 25940539, 2015). "In this respect, in cancer cells with AXL overexpression, 33 genes involved in EMT were found up-regulated with a median fold-change of 22.7." (PMID 25966280, 2015). "BergenBio & Rigel Pharmaceuticals have recently launched a clinical trial (phase I) to evaluate the AXL inhibitor BGB324 (formerly R428) in cancer patients." (PMID 25593196, 2015). "To investigate the role of AXL in cancer progression we used a panel of human CRC cell lines were we detected AXL protein expression and activation." (PMID 25966280, 2015). "These include MET, which has been shown to heterodimerize with AXL to regulate cancer cell migration/invasion." (PMID 26356563, 2015). "For example, we developed a humanized antibody hMAb173 that effectively degrades AXL and inhibits proliferation/migration/invasion in AXL positive cancer cells, including TNBC cells as investigated in the current study." (PMID 26356563, 2015). "High expression of AXL has been observed in various types of cancer patients and proposed as a poor prognostic biomarker." (PMID 25760142, 2015). "Our observations support previous reports that the role of AXL in cancer is a consequence of receptor overexpression and/or its inappropriate activation." (PMID 26573603, 2015). "This review highlights the data supporting AXL as a novel treatment candidate in a variety of cancers as well as the current status of drug development targeting the AXL/GAS6 axis and future perspectives in this emerging field." (PMID 25337673, 2014). "The extracellular portion of AXL can be cleaved off from the membrane to generate soluble AXL (sAXL), which is present in conditioned media from cancer cells as well as in human sera." (PMID 25551830, 2014). "Deficiencies in TAM signaling have been shown to play key roles in sustained immune activation and chronic inflammation raising some concerns about the use of AXL inhibitors in cancer therapy." (PMID 25337673, 2014). "Findings from other and our present data clearly indicate that increased expression of AXL is a common feature of cancer cells." (PMID 22141136, 2011). "Overall, our results demonstrate that N-glycosylation is essential for AXL stability, localization, and oncogenic signaling, offering new insights into the role glycosylation in regulating receptor tyrosine kinases function in cancer." (PMID 42055283, 2026).
cancer (continued). "Moreover, AXL is a key driver of stemness in cancer cells, facilitating self-renewal and contributing to the long-term maintenance of tumors such as breast cancer." (PMID 41563267, 2026). "Similarly, a promising area of investigation in SETD2-mutated cancer is into immune checkpoint expression, such as HAVCR2, CTLA-4, or TIGIT or biomarkers such as CDCP1 and AXL." (PMID 41228333, 2025). "AXL activation has been previously implicated in longer‐term resistance of AML and other cancers." (PMID 39395205, 2025). "Human clinical trials are focusing on AXL inhibitors mainly in cancer." (PMID 41233312, 2025). "A pathway that is implicated in dormancy maintenance across multiple cancer types in bone is GAS6 expressed by osteoblast lineage cells and also breast cancer cells, binding to TYRO3, AXL or MER (TAM) tyrosine kinase receptors, although the type of receptor expressed varies across cancer types." (PMID 41091336, 2025). "Examining the co-expression patterns of EGFR and AXL in various cancers could provide valuable insights into potential biomarkers." (PMID 39924521, 2025). "Recent studies have highlighted the role of AXL in modulating glucose metabolism in cancer cells." (PMID 39924521, 2025). "Overall, these findings suggest that using inhibitors targeting both AXL and c-MET may be a promising strategy for preventing the progression and metastasis of cancers driven by AXL/c-MET signaling." (PMID 39924521, 2025). "AXL inhibitors are currently in clinical development; thus, there is a strong need to systematically explore their antitumor effects and potential cellular mechanisms of action to avoid possible side effects and benefit more cancer patients." (PMID 40157901, 2025). "Among all TAM receptors, AXL is most frequently overactivated in various cancer types." (PMID 40044635, 2025). "Therefore, AXL inhibition has emerged as a promising strategy for developing targeted anticancer agents against various cancers." (PMID 40157901, 2025). "Given the insights, a potentially viable treatment approach for overcoming and delaying acquired resistance in cancer may involve simultaneously targeting AXL and other RTKs that share similar downstream signaling networks through combination therapy." (PMID 39924521, 2025). "Consequently, activated AXL contributes to VEGF-A/VEGFR2-dependent cancer cell migration, tube formation, vascular permeability, and corneal neovascularization." (PMID 39924521, 2025). "As AXL has been implicated in both long‐term resistance in AML and adaptive resistance in other cancers, we hypothesized that targeting AXL could wholly or at least partially decrease the previously observed rapid rebound." (PMID 39395205, 2025). "AXL has recently emerged as a promising therapeutic target for the treatment of many cancer types." (PMID 40157901, 2025). "Compared to EGFR, cancer cells rely more on AXL for downstream pro-survival signaling in TNBC." (PMID 40560045, 2025). "Therefore, co-targeting AXL along with other RTKs presents a promising strategy to address the challenges associated with RTK signaling rewiring and improve cancer management." (PMID 39924521, 2025). "AXL is a RTK that is involved in resistance in several cancers." (PMID 39395205, 2025). "Radiolabeled sdAb20-based imaging may be an accurate and non-invasive method to monitor AXL expression in cancer patients, paving the way for personalized treatment and increased effectiveness of AXL inhibitors." (PMID 38773967, 2024). "Interestingly, human CNK2 and the HYP homolog SAMD12 have recently been shown to control cancer cell migration by mediating ARF6 activation induced by AXL signaling." (PMID 38388830, 2024). "In addition, in a novel strategy, AXL was used as a cancer antigen for chimeric antigen receptor (CAR)-T cell treatment more recently." (PMID 38391974, 2024). "Here, we first demonstrated C-mannosylation of AXL at Trp320 in various cancer cell lines." (PMID 39660536, 2024).
cancer (continued). "AXL signaling has been linked to several human cancer cases, and studies have demonstrated a negative correlation between overexpression as well as metastasis and prognosis." (PMID 38391974, 2024). "Several studies have demonstrated that AXL is upregulated in various cancer types, including BC." (PMID 37760491, 2023). "Of potential interest, kisspeptin increases transcriptional expression of AXL in some cancers." (PMID 37396176, 2023). "Most studies have focused on the aberrant expression of AXL in various cancers." (PMID 37116196, 2023). "Finally, TNFSF10—TNFRSF10B (TRIAL—TRIAL-R), SIRPA—CD47 (“don't eat me”), C5AR1—RPS19, and GAS6—AXL act as negative regulators of the innate immune system by inhibiting cytokine responses, phagocytosis of cancer cells, and promoting the immunosuppressive TME." (PMID 37823774, 2023). "Our previous studies revealed that AXL not only plays a critical role in promoting cancer cell invasiveness but may also contribute to chemoresistance." (PMID 37834326, 2023). "Also, multiple studies have reported that overexpression of AXL promotes metastasis in various cancers, including oral cancer." (PMID 36650344, 2023). "Published clinical studies of GAS6/AXL related drugs for cancer." (PMID 37265798, 2023). "As 13R4a does not recognize any target in mice, we then used D4a, an antibody against human (but not mouse) AXL, and three human cell lines with different AXL expression: immortalized myoblasts (low AXL expression) and MDA-MB-231 and CFPAC cancer cells (high AXL expression)." (PMID 37697076, 2023). "This review aims to describe the structure of AXL and its expression regulation, summarize the expression pattern of AXL in cancers, and further discuss the role of AXL plays in cancer occurrence development, particularly in anti-cancer drug resistance." (PMID 37328828, 2023). "Ample evidence suggests AXL mediates resistance to multiple anti-cancer drugs." (PMID 37328828, 2023). "AXL is a receptor tyrosine kinase that is often overexpressed in cancers." (PMID 37349576, 2023). "The tyrosine kinase receptor AXL is tightly coexpressed with FRA-1 in a variety of invasive cancer cell lines, including muscle-invasive bladder carcinoma cells, in which AXL was originally identified as an FRA-1 transcriptional target involved in the control of cancer cell motility." (PMID 37176013, 2023). "Furthermore, AXL is also closely associated with epithelial-mesenchymal transition (EMT), drug resistance, and cancer stemness." (PMID 37960146, 2023). "Recent studies revealed that reducing AXL expression can weaken cancer cells' drug resistance, indicating that AXL may be a promising target for anti-cancer drug treatment." (PMID 37328828, 2023). "Additionally, we will discuss the diverse functions of AXL in mediating cancer drug resistance and the potential of AXL inhibitors in cancer treatment." (PMID 37328828, 2023). "GAS6-CAR-T cells did not lyse TAM-low ASPC1 and BxPC3 cell lines, suggesting it may spare normal tissues expressing lower AXL relative to cancer tissues." (PMID 37475048, 2023). "Bemcentinib, on the other hand, is a selective inhibitor of AXL receptor tyrosine kinase (UFO) that may be taken orally and has the potential to have anti-cancer effects." (PMID 37975995, 2023). "AXL overexpression in GI cancers has been associated with resistance to both targeted and non-targeted anti-cancer therapies." (PMID 37469409, 2023). "Activation of AXL represents a significant mechanism of acquired resistance in cancer cells." (PMID 37834326, 2023). "AXL-targeted therapies either as particular agents or in combination with conventional chemotherapy or other small molecule inhibitors have a promising opportunity to increase the survival rate of cancer patients." (PMID 37469409, 2023).
cancer (continued). "AXL and fibroblast growth factor receptor (FGFR) are involved in this alternative pathway since increased levels of FGFR and AXL are directly associated with cancer cell resistance to the TKI (sunitinib)." (PMID 37190141, 2023). "Consistent with the proposed role of AXL in cancer, Axl mutations and dysfunctional AXL protein are not widely implicated in the development of reproductive disorders." (PMID 37396176, 2023). "Furthermore, increased AXL mRNA and/or protein has been observed in other cancers, such as papillary thyroid carcinoma and pancreatic ductal adenocarcinoma (PDAC)." (PMID 37328828, 2023). "The expression of AXL can also contribute to therapy resistance in many cancer types." (PMID 36835239, 2023). "AXL is a member of the TAM (TYRO3, AXL, and MERTK) receptor tyrosine kinases family (RTKs), and its abnormal expression has been linked to clinicopathological features and poor prognosis of cancer patients." (PMID 37328828, 2023). "In human cancer, ADAM12 stratifies patients with high levels of hypoxia and innate resistance mechanisms, as well as factors associated with a poor prognosis and drug resistance such as AXL." (PMID 37798557, 2023). "Overall, these findings suggest that AXL may play a critical role in promoting resistance to cancer treatments and further highlight the potential of AXL as a therapeutic target for cancer treatment." (PMID 37328828, 2023). "Furthermore, AXL- and SAM68-deficient or R428-treated cancer cells had elevated levels of cholesterol, indicating a protective cellular metabolic response against AXL inhibition-induced DNA damage." (PMID 37349576, 2023). "Overexpression of AXL has been correlated with disease aggressiveness in many cancers." (PMID 35572601, 2022). "Different AXL-mediated signaling pathways may support cell-autonomous or cell-to-cell mediated crosstalk during cancer progression." (PMID 35572601, 2022). "Hypoxia promotes AXL expression in cancer cells derived from solid and liquid tumors." (PMID 35572601, 2022). "The critical role of AXL makes it a promising target for cancer therapy." (PMID 35332208, 2022). "More important, AXL contributes to drug resistance in cancer treatment." (PMID 35406721, 2022). "However, further large-scale analysis will be required to validate the prognostic value of AXL expression in cancer." (PMID 35158733, 2022). "As discussed, there is now compelling preclinical evidence denoting the potential of targeting AXL to mediate sensitization of cancer cells to immune cell-mediated attack and diminish immunosuppression within the TIME, with beneficial additive or synergistic effects in combination with ICI." (PMID 35572601, 2022). "Importantly, depletion of neutrophils (αLy6G) abolished AXL activation on disseminated cancer cells." (PMID 35022267, 2022). "A plethora of EMT-aTFs regulated by TGF-ß signaling may upregulate AXL expression in various cancer systems." (PMID 35572601, 2022). "AXL is overexpressed in several cancer types and correlates with poor survival." (PMID 35406721, 2022). "Development of AXL as a biomarker of drug response could be used to personalize metformin-based cancer therapy." (PMID 35936716, 2022). "The majority of the internalized AXL is not degraded but recycled to specifically sustain the downstream activation of AKT at the plasma membrane, that may promote GAS6–AXL-induced cancer-cell migration and invasion." (PMID 35622156, 2022). "More fundamentally, there is a need to stratify cancers based on AXL dependency so as to select patients that could benefit the most from AXL-targeted therapies and avoid potential toxicity or resistance." (PMID 35158733, 2022). "The AXL receptor is a promising target for AXL-targeted cancer drugs." (PMID 36551940, 2022). "In addition to demonstrating the AXL/MHC I association in human tumors, the investigators reported associations with SNAIL upregulation and cancer-associated fibroblast signatures." (PMID 35572601, 2022).
cancer (continued). "Importantly, a study evaluating transcriptome analysis of 941 cancer cell lines found that high AXL mRNA levels indicate resistance to necroptosis while low RIPK3 mRNA levels predict resistance to necroptosis." (PMID 36186479, 2022). "Due to the high selectivity of R428, induction of apoptosis in the absence of AXL is limited, which provides R428 with the potential advantage of causing less side effects in cancer therapy." (PMID 35805163, 2022). "Some studies suggest that AXL could also be an interesting marker for patients’ survival of different cancer types and a recent meta-analysis supports these observations." (PMID 35158733, 2022). "AXL expression correlates strongly with EMT markers in various cancers." (PMID 35158733, 2022). "In addition, METTL3 stimulates epithelial-mesenchymal transition (EMT) of cancer cells by stimulating receptor tyrosine kinase AXL, thereby enhancing the invasion and metastasis of OC." (PMID 34484284, 2021). "Furthermore, inhibition of AXL has been shown to aid DNA repair-targeting treatment in several cancers." (PMID 33800547, 2021). "In situations where the accurate quantification of the target may be required, such as the monitoring of the expression level of cancer-related genes such as AXL, a more robust detection method may be needed." (PMID 34442532, 2021). "In recent years, AXL has been intensively studied in the context of cancer." (PMID 34638349, 2021). "Due to the role of AXL it has been proposed as target for cancer therapy." (PMID 34006939, 2021). "Several proteins involved in cytoskeleton rearrangement such as actin, TNS3, KIF23, CKAP2L, NEDD9 and PLEC were also hyperphosphorylated, indicating the known regulatory role of AXL in promoting cancer cell migration/invasion and inducing epithelial-mesenchymal transition (EMT)." (PMID 34439388, 2021). "AXL-RTK also promotes resistance to targeted cancer therapies." (PMID 34140003, 2021). "The association between AXL signaling and EMT has been reported in different cancer types." (PMID 34638349, 2021). "Importantly, AXL inhibition contributes to a potentially broader deregulation of angiogenesis as it reduces secretion of several other pro-angiogenic factors from cancer cells." (PMID 34884986, 2021). "Also different from quiescent AKT1low cancer cells described by the Ramaswamy group, AXL-positive cells are actively dividing." (PMID 34254585, 2021). "Recently, inhibition of AXL tyrosine kinases has become an important method for cancer treatment." (PMID 34831142, 2021). "The TAM family of RTKs has emerged as an important driver of cancer, and among this family, AXL has attracted the most attention as a molecule when expressed possesses prognostic value in several cancer types, including breast, ovarian, lung, and pancreatic cancer." (PMID 34638349, 2021). "This immunosuppressive effect of DCs is exerted through TAM signaling, and this immune response may be reinforced, especially in cancer cells as they overexpress AXL." (PMID 34778071, 2021). "As AXL is overexpressed in numerous cancer types, it has already been pursued as a drug target." (PMID 33420426, 2021). "This novel framework could inform the development of novel cancer treatments based on the targeting of both AXL-negative and AXL-positive cell populations." (PMID 34254585, 2021). "AXL is also highly expressed on a variety of cancer types, OS included, where it plays a central role in tumor proliferation, survival, stem cell phenotype, metastasis, and resistance to cancer therapy." (PMID 34440182, 2021). "Multiple signaling pathways involved in cell adhesion, cell-cell junctions and cytoskeleton rearrangement were also regulated by the activation of AXL, suggesting activation of AXL could regulate cancer cell migration and invasion." (PMID 34439388, 2021).